HOXB-AS2 (HOXB cluster antisense RNA 2)
Gene: Long non-coding RNA gene on chromosome 17 (48,557,262 to 48,560,333, forward strand). Ensembl gene ENSG00000239552.
Diseases named in the same sentence as HOXB-AS2 in open-access papers:
HOXB-AS2 is named in the same sentence as 1 disease in open-access papers, as found by Europe PMC text mining. Sharing a sentence is not in itself a finding about the gene and the disease. The quoted sentences say what the papers report.
atrial fibrillation (1 paper, 2021). A disorder characterized by an electrocardiographic finding of a supraventricular arrhythmia characterized by the replacement of consistent P waves by rapid oscillations or fibrillatory waves that vary in size, shape and timing and are accompanied by an irregular ventricular response. "HOXB-AS2 has been reported to be abnormally expressed in the epicardial adipose tissue in atrial fibrillation." (PMID 34367253, 2021).